FADS1 (fatty acid desaturase 1)
Description:
[Isoform 1]: Acts as a front-end fatty acyl-coenzyme A (CoA) desaturase that introduces a cis double bond at carbon 5 located between a preexisting double bond and the carboxyl end of the fatty acyl chain. Involved in biosynthesis of highly unsaturated fatty acids (HUFA) from the essential polyunsaturated fatty acids (PUFA) linoleic acid (LA) (18:2n-6) and alpha-linolenic acid (ALA) (18:3n-3) precursors. Specifically, desaturates dihomo-gamma-linoleoate (DGLA) (20:3n-6) and eicosatetraenoate (ETA) (20:4n-3) to generate arachidonate (AA) (20:4n-6) and eicosapentaenoate (EPA) (20:5n-3), respectively. As a rate limiting enzyme for DGLA (20:3n-6) and AA (20:4n-6)-derived eicosanoid biosynthesis, controls the metabolism of inflammatory lipids like prostaglandin E2, critical for efficient acute inflammatory response and maintenance of epithelium homeostasis. Contributes to membrane phospholipid biosynthesis by providing AA (20:4n-6) as a major acyl chain esterified into phospholipids. In particular, regulates phosphatidylinositol-4,5-bisphosphate levels, modulating inflammatory cytokine production in T-cells (By similarity). Also desaturates (11E)- octadecenoate (trans-vaccenoate)(18:1n-9), a metabolite in the biohydrogenation pathway of LA (18:2n-6) (By similarity). [Isoform 2]: Does not exhibit any catalytic activity toward 20:3n-6, but it may enhance FADS2 activity.
Synonyms: D5D; FADSD5; TU12; FADS6; LLCDL1
Tractability: Small molecule: a high-quality ligand is known. Antibody: UniProt predicts a signal peptide or a membrane-spanning region. PROTAC: ubiquitination databases record sites on it; its protein half-life has been measured; a small molecule that binds it is known.
Target class: Enzyme
Gene: Protein-coding gene on chromosome 11 (61,799,624 to 61,829,318, reverse strand). Ensembl gene ENSG00000149485.
Subcellular location: Endoplasmic reticulum membrane (Isoform 1); Mitochondrion; Endoplasmic reticulum membrane (Isoform 2)
Pathways (Reactome):
Metabolism: Linoleic acid (LA) metabolism; PPARA activates gene expression; alpha-linolenic acid (ALA) metabolism
Gene Ontology:
Molecular function: acyl-CoA (8-3)-desaturase activity; acyl-CoA 6-desaturase activity; oxidoreductase activity; C-5 sterol desaturase activity; omega-6 fatty acid desaturase activity
Biological process: cellular response to starvation; long-chain fatty acid biosynthetic process; unsaturated fatty acid biosynthetic process; alpha-linolenic acid metabolic process; cell-cell signaling; icosanoid biosynthetic process; linoleic acid metabolic process; phospholipid biosynthetic process; regulation of cell differentiation; regulation of DNA-templated transcription; lipid metabolic process
Cellular component: membrane; endoplasmic reticulum membrane; intracellular membrane-bounded organelle; mitochondrion
Genetic constraint (gnomAD): Loss-of-function variants: 16 observed, 56.78 expected, observed/expected ratio (o/e) 0.28, 90% interval 0.19 to 0.43. The upper end of that interval is the gene's LOEUF score, 0.43, which puts it in group 1 of 6, group 1 being the genes least tolerant of losing a copy. Missense variants: 381 observed, 614.63 expected, observed/expected ratio (o/e) 0.62, 90% interval 0.57 to 0.68. Synonymous variants: 234 observed, 240.56 expected, observed/expected ratio (o/e) 0.97, 90% interval 0.87 to 1.08.
Homologues: Orthologues: chimpanzee FADS1 (99% identical), macaque FADS1 (84% identical), rat Fads1 (79% identical), mouse Fads1 (79% identical), pig FADS1 (76% identical), guinea pig FADS1 (76% identical), dog FADS1 (67% identical), tropical clawed frog fads1 (58% identical), Caenorhabditis elegans fat-4 (24% identical), Caenorhabditis elegans fat-3 (23% identical). Paralogues in human: FADS2 (55% identical), FADS3 (47% identical), FADS6 (16% identical).
Diseases named in the same sentence as FADS1 in open-access papers:
FADS1 is named in the same sentence as 146 diseases in open-access papers, as found by Europe PMC text mining. Sharing a sentence is not in itself a finding about the gene and the disease. The quoted sentences say what the papers report.
Obesity (43 papers, 2016 to 2025). Accumulation of substantial excess body fat. "The decreased expression of Fads1 is associated with the increased total lipid content in the liver, as well as obesity, MAFLD, and other metabolic disorders." (PMID 40786039, 2025). "For example, rs174561, located in the precursor gene of miR-1908-5p and intronic to FADS1, both known to be associated with lipid and obesity traits, was associated with lipid metabolites." (PMID 39434104, 2024). "While Powell and colleagues showed that FADS1 deficiency is beneficial in improvements in obesity, diabetes, and atherosclerotic cardiovascular disease, another study demonstrated FADS1 deficiency worsens high-fat diet induced hepatic steatosis." (PMID 38732052, 2024). "FADS1-3 are reported to share genome-wide significant associations with almost all cardiometabolic phenotypes such as dyslipidemia, fatty liver, obesity, and T2D." (PMID 36837846, 2023). "Nevertheless, the results of genetic studies on Fads1 polymorphisms and obesity are often contradictory, with more effects observed in children compared with adolescents and adults, and it appears that other factors can still overcome the genetic influences." (PMID 37545582, 2023). "Some examples are SNVs at CREBRF and FADS1 that are associated with obesity, type 2 diabetes, and lipemic traits that are under selection in Samoans and Europeans, respectively." (PMID 36553518, 2022). "3-Hydroxy-3-Methylglutaryl-CoA Synthase 1 (HMGCS1) and Fatty Acid Desaturase (FADS1) where both identified as being overexpressed in obesity and linked to higher risks of developing type 2 diabetes." (PMID 28606124, 2017). "Therefore, FADS1-driven immune-inflammatory reprogramming in adipose tissue may be a potential mechanism linking obesity with elevated CRC risk." (PMID 41153716, 2025). "Finally, FADS1 emerged as a pivotal determinant linking obesity, MetS, and elevated CRC risk." (PMID 41153716, 2025). "Fads1 is involved in de novo lipogenesis in the liver, and its suppression has been shown to improve obesity-related biomarkers." (PMID 41374070, 2025). "In obesity, the downregulation of both Bmal1 and Fads1 leads to impaired coordination between Bmal1 and Clock, further compromising lipid metabolism regulation." (PMID 40924721, 2025). "The effect of the FADS1 rs174547 variant in subjects with the CC genotype showed minor increases in PUFA percentages and the O3I in the RBCs of individuals with obesity." (PMID 39458515, 2024). "The present study reported that subjects carrying the CC genotype of the FADS1 rs174547 variant showed a smaller increase in n-6, n-3, total PUFA, and EPA percentages in RBCs compared to TT genotype carriers, in subjects with obesity supplemented with n-3." (PMID 39458515, 2024). "FA desaturase (FADS1 and FADS2) polymorphisms are associated with Alzheimer’s disease, Acute Coronary Syndrome, Autism spectrum disorder and obesity." (PMID 36900123, 2023). "Minor alleles of various FADS1 (rs174545, rs174546, rs174548, and rs174553) and FADS2 (rs1535 and rs174583) genes have been associated with an increased risk of obesity in women with a lower BMI (less than 25.0 kg·m−2)." (PMID 35736500, 2022). "This correlation was modified by the FADS1/2 genetic variation in obese individuals participating in the Kuopio Obesity Surgery (KOBS) study." (PMID 35701670, 2022). "It is known that the FA metabolism changes in obesity: the desaturating enzyme activity of FADS2 appeared to increase while that of FADS1 appeared to be inhibited with the result of lower LCPUFA levels." (PMID 35177087, 2022). "To advance this area, we investigated if the commonly studied rs174537 SNP in the FADS1 gene was associated with immune cell profiles in abdominal or femoral subcutaneous adipose tissue (SAT) from men and women with obesity." (PMID 33595419, 2021).
Obesity (continued). "Among the 25 potential pleiotropic genes, two genes, GCKR, and FADS1, were suggested to be pleiotropic genes for type 2 diabetes, obesity and dyslipidemia based on the results of previous studies." (PMID 30110382, 2018). "In conclusion, minor allele carriers of FADS1 and FADS2 SNPs have an increased risk of obesity (p≤0.05)." (PMID 28598979, 2017). "Obesity disrupts 17-HDHA and PD1 biosynthesis; S. aureus infection in macrophages elevates COX-2/mPGES-1 but suppresses 15-LOX-1, impairing SPM production; and fatty acid desaturase 1 deficiency alters hepatic PUFA metabolism, limiting SPM synthesis." (PMID 41246324, 2025). "Furthermore, recent studies have indicated a positive interrelationship between enhanced FADS1 activity and obesity state." (PMID 38919749, 2024). "Another case–control studyreported an association between FADS1/rs174556,FADS2/rs174617, and obesity, by demonstrating that plasmalevels of omega-6 PUFAs and AA were higher in overweight and obese patients;however, the difference in ω-3 PUFA levels was not significant." (PMID 39076540, 2024). "SNPs of FADS2 (rs174593, rs174616, and rs175576) have been documented to play a role in the interaction of polyphenols with PUFA levels and parameters of obesity, while lower levels of TC, LDL-C, and HDL-C have been associated with the minor allele of FADS1 rs174547." (PMID 35736500, 2022). "To advance this area, we conducted an exploratory study to investigate whether the common rs174537 polymorphism in FADS1 was associated with immune cell profiles in abdominal and femoral SAT in individuals with obesity." (PMID 33595419, 2021). "In addition, there is evidence to suggest that altered FADS1 activity is at the interface between obesity and other major chronic diseases." (PMID 30884788, 2019). "DNA methylation levels in the CpG sites annotated to FADS2 and FADS1 were analyzed from liver samples of 95 obese participants of the Kuopio Obesity Surgery Study (34 men and 61 women, age 49.5 ± 7.7 years, BMI 43.0 ± 5.7 kg/m2) using the Infinium HumanMethylation450 BeadChip (Illumina)." (PMID 30654845, 2019). "In addition, FADS1/2 desaturase activity plays an important role in neuropsychiatric diseases (depression, bipolar disorder, dementia), metabolism (obesity, metabolic syndrome, type 2 diabetes), and cardiovascular diseases (arterial hypertension, coronary heart disease)." (PMID 37685937, 2023). "Two cohorts of men homozygous for the genotype of FADS1 (rs174550) were studied: FADSDIET2 dietary intervention study with ALA- and LA-enriched diets and Kuopio Obesity Surgery study (KOBS), respectively." (PMID 39218219, 2024). "Thus, our findings indicated that FADS1 rs174547 might be a useful tool to elucidate the genetic basis of obesity-related disease, and it might be a predictive marker to identify high-risk individuals for abnormal body fat distribution and dyslipidemia, especially in male subjects." (PMID 28359317, 2017). "Genetic variation, particularly in the FADS1, FADS2, and ELOVL2 genes, may significantly influence FA metabolism and the development of metabolic disorders such as obesity." (PMID 41002979, 2025). "The results showed that potential intermediates between omega-3 fatty acids or FADS1/FADS2 genes and cognitive function were mostly associated with metabolic or neurological diseases, such as non-insulin dependent diabetes, metabolic syndrome, obesity and Alzheimer’s disease." (PMID 38316767, 2024).
metabolic syndrome (24 papers, 2009 to 2025). A cluster of metabolic risk factors for CARDIOVASCULAR DISEASES and TYPE 2 DIABETES MELLITUS. "Clinical studies have shown that patients with high FADS1 expression are more susceptible to metabolic syndrome and inflammatory reactions in response to dietary linoleic acid." (PMID 32454462, 2020). "Zabaneh and Balding reported that C11ORF10 and FADS1 were significantly associated with metabolic syndrome." (PMID 28744461, 2017). "In conclusion, our results allowed us to define the genetic variants most associated with serum PUFA concentrations in a Mediterranean population with metabolic syndrome and to confirm the strong association between the FADS1/FADS2 locus and omega-3 PUFA (specifically DHA) in this population." (PMID 31991592, 2020). "Some studies have found significant genotype–phenotype associations between variants of FADS1/FADS2 (rs174547, rs174575) genes and atherogenic dyslipidemia (high triacylglycerol (TAG) and low high-density lipoprotein cholesterol (HDL-C) levels)." (PMID 35736500, 2022). "Among these potential candidate genes, there are six genes (CETP, APOB, TMEM258, FADS2, FADS1, and PVRL2) associated with all phenotypes of dyslipidemia." (PMID 32425817, 2020). "This cross-sectional study aimed to determine the interaction of rs174547 in FADS1 gene with LA and ALA on metabolic syndrome (MetS) components." (PMID 31340443, 2019). "Among these genes, four of them, SORT1, FADS1, FADS2 and GALNT2, are recently reported as candidate genes at highly replicated genetic loci contributing to polygenic dyslipidemia." (PMID 20019805, 2009).
diabetes (20 papers, 2012 to 2025). "Although several studies have investigated FADS1 polymorphisms in general populations and various diseases, limited research has explored its association with diabetes." (PMID 40362254, 2025). "High FADS2 activity (Δ6-desaturase) and low FADS1 (Δ5-desaturase) activity have been associated with insulin resistance and, most importantly, have been shown to predict the development of diabetes." (PMID 41007350, 2025). "A recent systematic review showed that the relationship between PUFA intake, individual FA serum levels and diabetes risk is linked to polymorphisms of the genes expressing D5D and D6D (FADS1 and FADS2, respectively)." (PMID 30400149, 2018). "Alterations to the activity of the FADS2 and FADS1 gene products, delta-6 and delta-5 desaturase, respectively, has been associated with several diseases, such as diabetes, cardiovascular disease, inflammation, and cancer (breast, melanoma, lung)." (PMID 28506205, 2017). "Among single genetic variants consistently associated with diabetes-related metabolites, two (rs174550 (FADS1), rs3204953 (REV3L)) were significantly associated with type 2 diabetes in large-scale meta-analysis for type 2 diabetes." (PMID 28729637, 2017). "The top-ranked SNP was the FADS1-rs174547 T > C. This SNP was strongly associated with serum omega-3 concentrations even after additional adjustment for covariates (p = 3.34 × 10−14 in the model adjusted for sex, age, and diabetes)." (PMID 31991592, 2020). "Further, our finding of an inverse association of Δ5-desaturase (DGLA to AA) with GDM risk was consistent with an inverse causal relation of Δ5-desaturase activity encoded by the fatty acid desaturase 1 (FADS1) with diabetes risk in a mendelian randomization study." (PMID 31518348, 2019). "Haplotype reconstruction may be of particular importance in studies looking at insulin resistance measures or diabetes risk as D5D (FADS1) and D6D (FADS2) activities have been shown to have an opposite relationship with diabetes risk." (PMID 24455201, 2013). "Still, we did not detect a statistically significant interaction of nuts consumption, nor of LA/ALA intake and plasma phospholipid levels, and FADS1 in relation to diabetes risk." (PMID 40484934, 2025). "In this study, the mQTLs at FADS1, each with high minor allele frequency, between 0.33 and 0.42, displayed GxD interaction with SSB intake and total carbohydrate intake on T2D risk, and T2D-related phenotypes, i.e., glucose and HOMA-IR, in participants who were not using anti-diabetes medication." (PMID 41295283, 2025).
gastric cancer (20 papers, 2014 to 2025). A primary or metastatic malignant neoplasm involving the stomach. "In addition, we hypothesized that the risk of gastric cancer associated with dietary n-3 and n-6 PUFAs would vary according to FADS1 or FADS2 genetic variants." (PMID 29491470, 2018). "Thus, we examined whether dietary n-3 and n-6 PUFAs are associated with the risk of gastric cancer and further investigated whether fatty acid desaturases 1 and 2 (FADS1 and FADS2) modify this association." (PMID 29491470, 2018). "Studies have shown that in gastric cancer cells, the expressions of long-chain fatty acid protein 5 (ELOVL5) and fatty acid desaturase 1 (FADS1) discriminate the cellular susceptibility to ferroptosis." (PMID 39170694, 2024). "Specific overexpression of elongation of very long-chain fatty acid protein 5 (ELOVL5) and fatty acid desaturase 1 (FADS1) in mesenchymal gastric cancer cells, both involved in PUFAs synthesis, makes cancer cells particularly susceptible to ferroptosis." (PMID 38273826, 2023). "On the other hand, FADS1 expression was regulated by DNA methylation in a gastric cancer cell line as demonstrated by treating the cells with the demethylating agent 5-aza-2′-deoxycytidine, which increased by 23-fold FADS1 mRNA expression." (PMID 24579084, 2014). "Furthermore, elongation expression of extra-long-chain fatty acid protein 5 (ELOVL5) and fatty acid desaturase 1 (FADS1) is upregulated in mesenchymal gastric cancer cells (GCs), contributing to the development of ferroptosis." (PMID 37686016, 2023). "A study showed that in gastric cancer cells of the mesenchymal state, the expression of elongation of very-long-chain fatty acid protein 5 (ELOVL5) and fatty acid desaturase 1 (FADS1) was upregulated, resulting in ferroptosis sensitization, which was opposite in intestinal-type gastric cancer cells." (PMID 38007473, 2023). "Hypermethylation of the promoter region results in low expression of ELOVL5 and FADS1 in intestinal-type gastric cancer (GC) cells, which are resistant to ferroptosis, and after supplementation with AA, the cells become ferroptosis-sensitive." (PMID 35978815, 2022). "Therefore, we examined whether dietary n-3 and n-6 PUFAs are associated with the risk of gastric cancer and sought to determine whether FADS1 and FADS2 modify the association between PUFAs and the risk of gastric cancer." (PMID 29491470, 2018). "In gastric cancer, the mesenchymal subtype exhibits unique ferroptosis vulnerability mediated by very long-chain fatty acid protein 5 (ELOVL5) and fatty acid desaturase 1 (FADS1) dependent PUFA synthesis enhancement." (PMID 40892295, 2025). "It has been reported that inhibition of fatty acid desaturase-1 (FADS1) lowers the levels of AA and AdA in gastric cancer, thus resulting in tumor insensitivity to ferroptosis." (PMID 38459004, 2024). "In gastric cancer, it was shown that ELOVL5 and FADS1 enhance the sensitivity to ferroptosis, increasing anti-tumor effect." (PMID 38102129, 2023). "Similarly, in the case of gastric cancer, the expression of elongation of very long-chain fatty acid protein 5 (ELOVL5) and fatty acid desaturase 1 (FADS1), which are enzymes of the PUFA biosynthesis pathway, determine ferroptosis sensitivity." (PMID 33499222, 2021). "The silencing of the DNA methylation of the elongation of very long-chain fatty acid protein 5 (ELOVL5) and fatty acid desaturase 1 (FADS1) leads to ferroptosis resistance, and these two enzymes are usually upregulated in mesenchymal-type gastric cancer cells (Lee J.-Y." (PMID 34568341, 2021). "Gastric cancer cells with high expression of elongation of very long-chain fatty acid protein 5 (ELOVL5) and fatty acid desaturase 1 (FADS1) are more sensitive to ferroptosis, while cells that highly expressed stearoyl-CoA Desaturase 1 (SCD1) exhibit ferroptosis resistance." (PMID 34796174, 2021).